ENSG00000306223 (novel transcript, antisense to TMEM158)
Gene: Long non-coding RNA gene on chromosome 3 (45,181,375 to 45,255,960, forward strand). Ensembl gene ENSG00000306223.
Gene Ontology:
Biological process: RNA processing
Cellular component: nucleolus